ZBP1 (Z-DNA binding protein 1)
Diseases named in the same sentence as ZBP1 in open-access papers (continued):
Sharing a sentence is not in itself a finding about the gene and the disease.
tumor (continued). "It has recently been shown that the ZBP1-MLKL necroptotic cascade induces cytoplasmic DNA accumulation in irradiated tumor cells and, in turn, autonomously activates cGAS-STING signaling, thus creating a positive feedback loop between these two pathways to drive persistent inflammation." (PMID 36089194, 2022). "ZBP1 deletion blocks tumor necroptosis during tumor development and inhibits tumor metastasis." (PMID 35754839, 2022). "In addition to mtDNA, the endogenous dsRNA remains the important ligand for ZBP1-mediated tumor immunity." (PMID 36142136, 2022). "Through genetic engineering, previous studies have applied ZBP1 to tumor therapy." (PMID 36142136, 2022). "The role of ZBP1 in tumour progression and metastasis is unclear." (PMID 36186436, 2022). "Therefore, our study reveals ZBP1 as the key regulator of tumor necroptosis and provides a potential drug target for controlling tumor metastasis." (PMID 33976222, 2021). "We showed that glucose deprivation triggers ZBP1-depedent necroptosis in tumor cells." (PMID 33976222, 2021). "Importantly, we demonstrated that ZBP1 is the key mediator of tumor necroptosis during tumor development in both MVT-1 and B16 syngeneic orthotopic cancer models and that ZBP1 deletion inhibits tumor metastasis in MVT-1 model." (PMID 33976222, 2021). "Therefore, our study reveals ZBP1 as the key regulator of tumor necroptosis during tumor development." (PMID 33976222, 2021). "Among the most significantly induced genes was Zbp1, a necroptosis effector linking innate immune sensing to immunogenic cell death, which has previously been shown to be a critical mediator of DNA damage-induced tumor suppression and anti-tumor immunity 37,38,45,46." (PMID 41282221, 2025). "Therefore, a multidimensional therapeutic strategy integrating the on‐demand regulation of ROS, ZBP1 gene modulation, and alleviation of the hypoxic microenvironment may be the key to achieving both anti‐tumor and bone repair effects." (PMID 40908585, 2025). "ZBP1 may also stimulate radiation-induced tumor cell phagocytosis, as a recent study has shown that inhibiting the phagocytosis inhibitor CD47 resulted in expansion of APCs and effector T cell responses in distant, non-irradiated tumors to potentiate abscopal responses." (PMID 41282221, 2025). "In addition, ZBP1 is a key regulator of tumor cell necroptosis." (PMID 37759572, 2023). "We confirmed that ZBP1 expression could be induced by IFNs in MVT-1 tumor cells." (PMID 33976222, 2021). "Therefore, ZBP1 is essential for tumor necroptosis during tumor development in these cancer models." (PMID 33976222, 2021). "By establishing a Zbp1 knockout mouse model integrated with scRNA-seq and functional validation, ZBP1 was identified as a pivotal bridging molecule in CAF–tumor cell interactions, positioning it as a key regulator of the TME and a driver of OSCC development." (PMID 41430036, 2025). "BX471 treatment significantly reduced tumor volume in WT mice, whereas recombinant CCL7 supplementation markedly increased tumors in Zbp1−/− mice." (PMID 41430036, 2025). "The expression and functional status of critical molecules comprising the PANoptosome, including ZBP1, RIPK1, RIPK3, CASP8, and ASC, can have a bidirectional impact on tumor survival, immune recognition, or tumor cell death." (PMID 40422233, 2025). "CASP8 and PGAM5 were identified as potential biomarkers among these, while previous studies have shown that ZBP1, TLR3, and PYGL contribute to tumor progression in KIRC." (PMID 40969770, 2025). "Collectively, ZBP1 broadly influences the TME by regulating stromal cell functions, inflammatory responses, immune evasion, and cell death pathways, thereby promoting tumor initiation, progression, and metastasis." (PMID 41430036, 2025). "ZBP1, originally named DLM-1, was initially discovered as a kind of tumor-related protein that functions in the host response to neoplasia." (PMID 38343534, 2024).
tumor (continued). "ZBP1 (also known as DAI) is the latest in PRRs and was identified as DLM-1 in tumor-activated macrophages." (PMID 39057788, 2024). "Studies indicate that directing interventions towards ZBP1, caspases, NLRP3, RIPK1, and RIPK3 can trigger a robust anti-tumor immune response, facilitating the efficient eradication of cancer cells." (PMID 38553639, 2024). "In the context of cancer, increased expression of A ADAR1-p150 has been demonstrated to restrict the binding of ZBP1 and RIPK3, consequently suppressing ZBP1-mediated PANoptosis to facilitate tumor growth." (PMID 38553639, 2024). "Moreover, the specific mechanism of ZBP1-mediated PCD in tumor cells remains unclear." (PMID 36845119, 2023). "FASLG, TNFRSF1B, GATA3, TARDBP, ZBP1, TNFRSF21, and TLR3 are mainly expressed in multiple immune cell types, and immune cells have a role in TME to inhibit tumor progression." (PMID 35899194, 2022). "The VACV expressing ZBP1 induces T cell infiltration (especially TAA-specific T cells) which establishes a powerful antitumor immune response system and strongly controls tumor volume." (PMID 36142136, 2022). "It is a kind of tumor-related protein strongly induced by LFN-γ or lipopolysaccharides (LPS), and the study suggested that ZBP1 plays a role in host response in neoplasia." (PMID 36615244, 2022). "Further, during radiotherapy, ZBP1-MLKL necroptosis promotes STING activation and type I IFN response in tumor cells accumulating cytoplasmic mtDNA." (PMID 36615244, 2022). "We found that most of the highly expressed NRGs in tumor tissues have CNV gain, such as TRIM11, ZBP1." (PMID 36059470, 2022). "Deletion of ZBP1 inhibited the activation of cGAS-STING signaling and priming of CD8+ T cells in tumor cells with radiation treatment." (PMID 36142136, 2022). "Examining the effect of ZBP1 deletion on lung metastasis, we found that mice implanted with CRISPR CT tumor cells had high lung metastasis whereas mice with ZBP1 KO MVT-1 cells had little lung metastasis." (PMID 33976222, 2021). "While there is a modest decrease of RIPK1 mRNA level in tumors, the mRNA levels of ZBP1 and RIPK3 are significantly increased in isolated tumor cells." (PMID 33976222, 2021). "While both RIPK1 and ZBP1 are capable of recruiting RIPK3 to mediate necroptosis, our results indicate that there is little redundancy among these two proteins in mediating tumor necroptosis during tumor development." (PMID 33976222, 2021). "We found that the levels of ZBP1 and RIPK3 expression are dramatically elevated in necrotic tumors during tumor development." (PMID 33976222, 2021). "Moreover, transcriptomic and Q-PCR analyses showed increased expression of Stat1, Zbp1, Parp14, Irf1, and Tifa along with decreased Eif4e2 in the SOR treatment group compared to the tumor control group." (PMID 42194025, 2026). "This study identified the pro-tumorigenic role of ZBP1 in OSCC and elucidated its molecular mechanism in enhancing tumor cell proliferation, migration, and invasion by regulating the CCL7–CCR1 chemokine axis between CAFs and tumor cells." (PMID 41430036, 2025). "In contrast, the expression or activation state of PANoptosis regulators (e.g., ZBP1, RIPK3, and caspase-8) can be altered by factors such as hypoxia, metabolic stress, and DNA damage in the tumor microenvironment, potentially suppressing or reprogramming PANoptosome formation." (PMID 40422233, 2025). "The expression and functional status of key molecules within the PANoptosome, such as ZBP1, RIPK1, RIPK3, CASP8, and ASC, may influence tumor viability and immune detection." (PMID 40422233, 2025). "Moreover, components of the PANoptosome, such as ZBP1 and AIM2, act as innate immune sensors that detect tumor-derived stress signals, initiating cell death and inflammation." (PMID 40422233, 2025). "Consistent with a previous study, we found ZBP1 expression was low or absent in tumor tissue, which suggests ZBP1-derived PANoptosis is most likely activated by chemotherapy in noncancerous tissues." (PMID 39465258, 2024).
tumor (continued). "FADD protein level was overexpressed, while ZBP1 protein level was nearly not expressed in tumor tissues." (PMID 38684755, 2024). "ZBP1 and RIPK3 also play important roles in tumor development." (PMID 37501725, 2023). "Indeed, ADAR1 inhibits ZBP1-mediated activation of NLPR3 inflammatory vesicles and cell death by competitively binding to ZBP1 with RIPK3, ultimately leading to tumor development." (PMID 37771585, 2023). "Furthermore, ZBP1 also upregulated IFN expression and activated the downstream STING pathway in necrotic tumor tissues." (PMID 37771585, 2023). "It is speculated that MYCN and ZBP1 will affect the similarity between KIRC cells and stem cells in different degrees, which means that they will affect the progress of tumor." (PMID 37878133, 2023). "In the absence of ZBP1, both the process of tumor necrosis and the suppression of metastasis are prevented." (PMID 38111587, 2023). "GEGFR, CD40, SPATA2, ZBP1, ID1, and MYC showed a significant CNV amplification in most tumour types; however, TLR3, PDHB, FAS, and MAP3K showed a significant CNV deletion in most tumour types." (PMID 36186436, 2022). "The inhibitory effects of radiotherapy on tumor growth in the MC38 mouse colon adenocarcinoma cell line and B16-SEY mouse melanoma cell line are directly related to the expression of MLKL in tumor cells, via ZBP1-mediated necroptosis signal transduction." (PMID 36615244, 2022). "To investigate the second role of ZBP1, namely induction of necroptosis, we knocked down ZBP1 in B16F10 tumor cells and evaluated their cell cycle distribution and cellular stress levels, as monitored by quantitative image-based cytometry (QIBC) and γH2AX induction." (PMID 35361802, 2022). "Consistent with our findings with tumor lysates, the levels of ZBP1 and RIPK3, but not RIPK1, are dramatically increased in GFP-MVT-1 cells isolated from tumors compared to that in cultured cells." (PMID 33976222, 2021). "The presence of the WT, not the Zα2 mutant, ZBP1 protein also reduced the cleavage of Casp-3 in tumor cells." (PMID 33976222, 2021). "Alternative approaches to enhance necroptosis signaling in tumor cells may include manipulation of ADAR1, which was shown to mask ZBP1-driven necroptosis, or therapeutic induction of IFN-I signaling in the TME as MLKL and other critical components are IFN-stimulated genes." (PMID 40345706, 2025). "Therefore, it comes as no surprise that ZBP1 is now considered an important signaling target in tumor therapeutic strategies." (PMID 38553639, 2024). "While this decrease of RIPK1 level in tumor cells may accelerate ZBP1-induced tumor necroptosis, loss of RIPK1 combined with the increase of ZBP1 expression is not sufficient to trigger necroptosis in tumor cells as observed in RIPK1 KO MVT-1 tumors." (PMID 33976222, 2021). "Studies based on MVT-1 breast cancer models demonstrated that ZBP1, rather than RIPK1, mediates tumor necroptosis." (PMID 36615244, 2022). "Here, we report that Z-DNA-binding protein 1 (ZBP1), not RIPK1, mediates tumor necroptosis during tumor development in preclinical cancer models." (PMID 33976222, 2021). "In this current study, we report that Z-DNA-binding protein 1 (ZBP1), not RIPK1, mediates necroptosis of tumor cells during tumor development in preclinical cancer models." (PMID 33976222, 2021). "Nevertheless, our work reveals ZBP1, not RIPK1, as the key mediator upstream of RIPK3 in tumor necroptosis and provide new insights about the regulation of tumor necroptosis during tumor development." (PMID 33976222, 2021). "We found that ZBP1 deletion does not affect in vitro and in vivo proliferation of MVT-1 cells and MVT-1 tumor growth." (PMID 33976222, 2021). "Importantly, ZBP1, not RIPK1, deletion blocks tumor necroptosis during tumor development and inhibits metastasis." (PMID 33976222, 2021).
cancer (58 papers, 2015 to 2026). A tumor composed of atypical neoplastic, often pleomorphic cells that invade other tissues. "Spliceosome inhibition induced potent ZBP1-dependent cell death in cancer-associated fibroblasts, which was essential for enhancing immunotherapy response in mouse models of SCLC." (PMID 41046514, 2025). "ADAR1i-124 activated MDA5 and ZBP1 pathways and dose-dependently inhibited viability across different types of cancer cell lines." (PMID 41608661, 2026). "In a recent study, we discovered CBL0137, a curaxin ligand, to enhance cancer immunotherapy by inducing Z-DNA formation and activating the Z-DNA-binding protein ZBP1." (PMID 41665010, 2026). "Ultimately, we delve into strategies for targeting PANoptosis in cancer therapy, including targeting various molecules in the PANoptosis pathway, such as ZBP1, RIPK1, RIPK3, Caspases and other novel strategies like nanoinducers and viral vectors." (PMID 40364845, 2025). "This study offers novel insights into the bidirectional regulation of ROS and the dual functionality of ZBP1, marking a major advancement in the development of multifunctional biomaterials for cancer therapy and bone regeneration." (PMID 40908585, 2025). "In another study, CASP6 facilitated ZBP1-mediated inflammasome activation, PANoptosis cell death, and host defense, opening additional avenues for treating cancer, infectious, and autoinflammatory diseases." (PMID 38169587, 2024). "Upregulation of ZBP1 impaired the activity of cancer-related pathways, such as Hedgehog and WNT signaling pathways." (PMID 38684755, 2024). "ADAR1 enables to mask the cancer immunotherapeutic promise of ZBP1-triggered necroptotic cell deaths." (PMID 38468359, 2024). "Further investigation revealed that ZBP1-mediated PANoptosis plays an important role in the antitumor effects of oHSV in cancer." (PMID 38693119, 2024). "Previous studies have revealed that overexpression of ZBP1 significantly promotes PANoptosis in cancer cells." (PMID 38967843, 2024). "A small molecule (3a-3l) based on quinoline induced DNA damage in cancer cells, and the resulting Z-form DNA inhibited the necrotic apoptosis mediated by apoptosis-inducing ZBP1." (PMID 39614405, 2024). "We note that CDK1 regulates pyrodeath, apoptosis, and necrosis of cancer cells (PANoptosis) by binding to PANoptosomes in a ZBP1-dependent manner." (PMID 38967843, 2024). "The results of this study showed that compared with normal tissues, the expression of CDKN2A and ZBP1 in cancer cells was significantly increased, while the expression of MYCN was on the contrary." (PMID 37878133, 2023). "Understanding the underlying mechanisms determining beneficial and detrimental effects of ZBP1 in cancer remains an important challenge for future studies, but recent work has begun to provide insight into this question." (PMID 37450010, 2023). "A recent study successfully explored a means of using a Z-DNA formation-triggering small molecule in a cancer model to sensitize tumor cells to ZBP1 activation." (PMID 36040212, 2022). "The upregulation of ZBP1 expression was correlated with sensitivity of cancer cells to ceritinib (LDK-378), alectinib, and brigatinib." (PMID 35165523, 2022). "mtDNA has been reported to release to the cytosol of cancer cells that bear necroptosis and ZBP1 senses the cytosolic mtDNA for the initiation of cancer necroptosis under glucose deprivation or stress condition 53-55." (PMID 35165523, 2022). "Cancer cells with higher ZBP1 expressions were more sensitive to the following drugs including LDK-378, alectinib, and brigatinib." (PMID 35165523, 2022). "Utilizing a ZBP1-knockout mouse model coupled with single-cell RNA sequencing analysis, ZBP1 deficiency was found to significantly suppress OSCC initiation and progression, underscoring ZBP1’s critical role in modulating the TME to facilitate cancer progression." (PMID 41430036, 2025). "ZBP1, in particular, plays a pivotal role in multiple cancers." (PMID 40148674, 2025).
cancer (continued). "The functions and roles of ZBP1 in cancer have also been recently discovered." (PMID 41299204, 2025). "ADAR1 hides ZBP1‐driven necroptosis's potential as a cancer immunotherapeutic." (PMID 41299204, 2025). "In summary, our study not only unravels critical aspects of ZBP1 function in antiviral immunity but also opens avenues for exploring its implications in pathological conditions such as cancer, thus contributing to the broader landscape of immune regulation and disease therapeutics." (PMID 38982083, 2024). "To determine whether ZBP1-derived PANoptosome assembly was triggered by chemotherapy in cancer patients, we performed PLA assay in colonic tissues to examine the association between ZBP1 and RIPK3 or Casp-6, respectively." (PMID 39465258, 2024). "In addition, FADD and ZBP1 played a crucial role in various cancer-related pathways, such as the MAPK, WNT, and MTOR signaling pathways." (PMID 38684755, 2024). "Furthermore, as ZBP1 expression is largely restricted to normal tissues in cancer patients, our findings suggest that ZBP1-derived PANoptosis contributes to chemotherapy-induced toxicity." (PMID 39465258, 2024). "Additionally, ZBP1 has interesting roles in cancer and other disease settings and is emerging as an attractive target for therapy." (PMID 37450010, 2023). "The role of ZBP1 in cancer is further determined by interactions with treatments and/or drugs." (PMID 37450010, 2023). "In addition, ZBP1 also plays an important role in regulating necroptosis in other human diseases, such as cancer and systemic inflammatory disease." (PMID 36615244, 2022). "Therapeutic activation of ZBP1-induced necroptosis brings new perspectives to the field of cancer." (PMID 36204681, 2022). "In contrast, the ten node genes in the mammary glands of the offspring of dams fed the CON diet were linked to changes in the expression of genes indicative of reduced cancer risk (downregulation of DPF3, SNORA41) and improved immune functions (upregulation of ZBP1, ZFP683; downregulation of EGR3)." (PMID 28673325, 2017). "The prognosis-associated PANoptosis-related genes (ZBP1, MAP3K7, and RBCK1) were highly elevated in the low-risk group and less expressed in the high-risk group, suggesting the participation of PANoptosis in cancer progression and as a potential target for therapeutic intervention in cancers." (PMID 38169587, 2024). "In addition, FADD could prevent the spontaneous expression of ZBP1, and then inhibit necroptosis of cancer cells." (PMID 38684755, 2024). "However, the endogenous activation of ZBP1 also has a positive effect in the setting of cancer." (PMID 36142136, 2022). "Similarly, a role of ADAR1 and ZBP1 has been reported in cancer." (PMID 36204681, 2022). "Upstream sensors like ZBP1, AIM2, and RIPK1, along with regulators identified in cancer-related PANoptosis studies, such as IRF1, ADAR, MAP3K7, and NFS1, were also incorporated for their significant regulatory roles." (PMID 39901195, 2025). "This offers important information on the functions of ZBP1 and ADAR1, informing potential therapeutic strategies for cancer and other diseases." (PMID 38169587, 2024). "AIM2, ZBP1, STAT1, and FAS mediate the immune response and play important roles in a variety of diseases, cancers, and infections." (PMID 37205113, 2023). "The results showed that MLKL had a strong positive correlation with CASP8, ZBP1, FASLG, RIPK1, and RIPK3 in all 33 cancer types, and RIPK3 was also strongly correlated with CASP8, MLKL, and ZBP1." (PMID 37000317, 2023). "Our findings showed that many important necroptosis molecules in the pan-cancer, including PLK1, MLKL, FASLG, and ZBP1, demonstrated a high level of activation in the apoptosis signaling pathway." (PMID 37000317, 2023). "GSDMC, GSDMD, GSDME, ZBP1, AIM2, DHX9 and NLRP3 demonstrated significant amplification across cancers." (PMID 36605187, 2022).